BPIFA4P (BPI fold containing family A member 4, pseudogene)
Description:
Major protein in sweat, has surfactant properties.
Synonyms: BASE; LATH
Gene: Transcribed unprocessed pseudogene on chromosome 20 (33,198,212 to 33,207,741, forward strand). Ensembl gene ENSG00000183566.
Subcellular location: Secreted